EGFR (epidermal growth factor receptor)
Diseases named in the same sentence as EGFR in open-access papers (continued):
Sharing a sentence is not in itself a finding about the gene and the disease.
tumor (continued). "We assessed whether LIPI, in combination with baseline clinical characteristics, can guide first-line treatment selection between pembrolizumab (P) and pembrolizumab plus platinum-based chemotherapy (PCT) in patients with PD-L1 tumor proportion score (TPS) ≥ 50% and EGFR/ALK/ROS1 wild-type." (PMID 40429538, 2025). "Furthermore, changes within the tumor microenvironment have been identified as a key contributor to EGFR-TKI resistance, further constraining the therapeutic potential of relying solely on EGFR-TKIs." (PMID 40003951, 2025). "As expected, DT treatment had no impact on tumor growth rate in WT EGFR-DEL mice." (PMID 39979425, 2025). "Unlike EGFR‐mutant tumours, which exhibit relatively uniform biology and high therapeutic sensitivity, KRAS‐mutant NSCLC is characterised by profound molecular heterogeneity, divergent co‐mutational profiles (e.g., STK11, KEAP1), and dynamic crosstalk with the tumour microenvironment (TME)." (PMID 41025426, 2025). "Integrating these features with patient-specific molecular and genetic profiles (e.g., IDH mutation status, MGMT promoter methylation, EGFR amplification, TERT promoter mutations) allows for non-invasive prediction of tumor biology, prognosis, and potential treatment response." (PMID 41465586, 2025). "Despite extensive efforts, EGFR-targeted therapies (e.g., tyrosine kinase inhibitors, monoclonal antibodies, and vaccine-based approaches like rindopepimut) have shown limited efficacy in clinical trials, largely due to challenges in BBB penetration and intrinsic tumor resistance." (PMID 41346390, 2025). "The lack of EGFR activation in nonparenchymal cells could lead to delay of the cytokines expression, inflammatory process and tumor lesion development observed in these murine models." (PMID 39966897, 2025). "In conclusion, this study demonstrated that PD‐L1, PD‐L2, and EGFR expression changed in 30%–40% of recurrent tumors, suggesting that marker expression in naive tumor specimens may not accurately reflect their status at recurrence." (PMID 40156197, 2025). "Studies on the mechanisms of other tumors have found that B7-H7 may exert pro-tumor effects by activating the Janus kinase (JAK)/signal transducer and activator of transcription (STAT), PI3K/Akt, and epidermal growth factor receptor (EGFR)/mitogen-activated protein kinase (MAPK)/ERK pathways." (PMID 41179658, 2025). "In this case, the initial NGS identified the tumor as EGFR‐wild type, which may represent a false negative." (PMID 39967842, 2025). "Consequently, dual-targeting strategies combining EGFR inhibitors (e.g., gefitinib or erlotinib) with GPER antagonists may offer a more effective approach for reducing tumor burden and overcoming tamoxifen resistance in ERα−positive BC." (PMID 40641933, 2025). "However, it has been shown that EGFR signaling can promote a noninflamed tumor microenvironment, and inhibition of this receptor can stimulate the infiltration of inflammatory immune cells." (PMID 40846697, 2025). "In addition, a mask is fused to each of the EGFR and CD3 binding domains through tumor protease cleavable linkers, and only when the molecule enters the tumor site and is recognized by the tumor protease can the peptide masks be released, ultimately generating the active molecules." (PMID 40510353, 2025). "Estrogen–growth factor crosstalk enhances EGFR phosphorylation and VEGF output, and preclinical studies show synergies when combining anti-estrogens with EGFR inhibitors (fulvestrant with erlotinib/vandetanib), including reduced VEGF secretion and tumor growth suppression." (PMID 40868244, 2025). "Metastatic or recurrent NSCLC without EGFR or ALK genomic tumor aberrations." (PMID 40342408, 2025). "Thus, we validated the correlation between PRDX1 and EGFR-TKI sensitivity through a series of in vitro experiments and found that PRDX1 inhibition along with osimertinib treatment resulted in synergistic inhibition of tumor growth." (PMID 40303499, 2025).
tumor (continued). "The expression levels of growth factor receptor genes (EGFR and ERBB2) and proliferation marker genes (PCNA and MKI67) in epithelial cells were not significantly higher in unaffected lung samples adjacent to a focal tumor compared with samples originating from healthy lungs." (PMID 40114924, 2025). "EGFR and Mcl-1 mRNA and protein expression levels were significantly higher in HNC tissues than in normal or margin tissues using datasets obtained from the Gene Expression Omnibus (GEO), the Cancer Genome Atlas (TCGA), and Clinical Proteomic Tumor Analysis Consortium (CPTAC)." (PMID 38888847, 2025). "The authors found that a combination of PAFR antagonist and EGFR inhibitor (AG1478) resulted in significantly increased inhibition of proliferation and invasion of CAOV3 and SKOV3 cell lines, as well as decreased growth of CAOV3 tumor xenografts in athymic nude mice compared to these drugs alone." (PMID 40160442, 2025). "In addition to EGFR, antibodies targeting angiogenesis have also been approved for treatment, such as bevacizumab and ramucirumab, which inhibit VEGF and VEGFR-2, respectively, significantly delaying tumor progression." (PMID 41361128, 2025). "This has been recently investigated clinically in a phase II, non-randomized study of 38 treatment-naive patients with advanced nonsquamous NSCLC, no EGFR, STIK11, MDM2, or ROS1 mutations, and a tumor mutational burden (TMB) > 10 mutations/megabase who received bevacizumab + atezolizumab." (PMID 40507214, 2025). "SPP1 might induce resistance to the EGFR‐TKI, and influence tumor immune infiltration." (PMID 41498045, 2025). "Indeed, we found that CMTM4 KD tumor was more responsive to PD-L1 antibodies treatment, which is resulted from reduced inflammatory cytokines productions from CMTM4 KD cells with retarded EGFR signaling." (PMID 39948411, 2025). "Interestingly, we also found that Lac dramatically reduced quantity of tumor-infiltrating Tregs both in the bone marrow reconstructed and non-reconstructed WT EGFR-DEL mice." (PMID 39979425, 2025). "In contrast to previous works on panitumumab nanohybrids developed for the treatment of EGFR‐positive cancers (vide supra), tumor growth arrest could not be achieved here with the trastuzumab nanohybrids." (PMID 40395357, 2025). "Tumor marker levels of EGFR mutant-positive and EGFR mutant-negative samples." (PMID 40510243, 2025). "To investigate if the observed heterogeneity in EGFR expression extends to cultured cell lines, we analyzed six cell lines derived from EGFR-mutant NSCLC patients, including three commercially available (PC-9, H1975, HCC4006) and three patient-tumor derived lines (DFCI-284, DFCI-243, DFCI-169)." (PMID 39747003, 2025). "Moreover, we observed that lower SSTR1 and SSTR2, but not CORT, expression levels were also displayed in tumours harbouring EGFR amplification, another aggressive sign in GBM, in the Gravendeel-cohort." (PMID 40268793, 2025). "Furthermore, EGF-targeted 5-FU-loaded PLGA NPs were developed to selectively target CRC cells expressing high levels of EGFR and showed higher rates of cytotoxicity and apoptosis and lower rates of tumor growth compared to non-targeted or non-NP treatments." (PMID 40076613, 2025). "Beyond tumor characteristics, age of diagnosis may have implications for treatment, as recent work has suggested lack of efficacy of EGFR inhibition among left-sided tumors in the early-onset population, although the reason for this is currently unknown." (PMID 40075683, 2025). "By targeting multiple surface proteins, this approach captures CTCs that may not express EpCAM but do express HER2 or EGFR, thereby encompassing a broader range of tumor cell phenotypes." (PMID 40076201, 2025). "In addition, the product is engineered with an EGFR safety switch and thus, cells can be quickly eliminated, if needed, by the administration of Cetuximab (anti-EGFR), approved by the U.S. Food and Drug Administration (FDA) for certain tumor types." (PMID 41462483, 2025).
tumor (continued). "Similarly, tuning the affinity of CAR to EGFR (a TAA robustly expressed on multiple human cancers) increases the ability of CAR-T cells to kill tumor cells rather than normal tissues with lower EGFR expression." (PMID 40148310, 2025). "High metastatic burden reflects aggressive tumor biology and likely contributes to rapid acquired resistance via clonal heterogeneity or bypass track activation, which even enhanced EGFR inhibition may not fully suppress long-term." (PMID 41479790, 2025). "In this context, the main strategies to boost NK-cell function against CRC could rely on the use of mAbs or BiKEs targeting CRC tumor antigens (e.g., EGFR, CEA, HER2, MUC-1 and LGR5) that can directly induce tumor cell death but also simultaneously trigger NK cell cytotoxicity via ADCC." (PMID 40607422, 2025). "In addition, we observed that EGF treatment barely impacted OX40 expression in T cells from tumor tissues, which might due to the negligible levels of EGF receptor (EGFR) gene expression in T cells compared with tumor ECs." (PMID 40026246, 2025). "We hypothesize that miRNAs that show significant up- or downregulation in GPs may regulate the expression of genes that are involved in the cell cycle (AURKB, CDC45, and CDK6), cell proliferation (EGFR and VEGFA), and angiogenesis (VEGFA) that support tumor growth." (PMID 40143207, 2025). "After EGFR binds to HER2 to form EGFR-HER2 heterodimers, it triggers receptor conformational changes, activates intracellular tyrosine kinase domains, significantly enhances downstream signals (such as MAPK, PI3K-AKT pathways), and promotes tumor cell proliferation, survival and metastasis." (PMID 40181988, 2025). "In this cancer type, IFIT1 overexpression promotes tumor growth and metastasis through epithelial-mesenchymal transition (EMT), while its silencing leads to opposite effects, likely through enhanced p-EGFR (phosphorylated epidermal growth factor receptor) recycling." (PMID 40564154, 2025). "Notably, one EGFR sample, EGFR_2 (with 10% tumor content), did not cluster with the other EGFR samples but rather with samples that had a higher number of identified phosphosites." (PMID 40621945, 2025). "Several RTKs, such as epidermal growth factor receptor (EGFR), PDGFR, and vascular endothelial growth factor receptor (VEGFR), are overexpressed and/or overactivated in HGG, further activating multiple signaling pathways involved in tumor growth, proliferation, and invasion." (PMID 40821315, 2025). "Notably, two new Tier IA events, absent in the primary tumor, were identified: an EGFR copy number gain (three copies) and a somatic JAK2 p.V617F mutation." (PMID 40842629, 2025). "First-generation EGFR tyrosine kinase inhibitors (TKIs), such as gefitinib and erlotinib, reversibly bind to and inhibit the tyrosine kinase domain of EGFR, thus blocking the downstream RAS-RAF-MEK-ERK and PI3K-AKT-mTOR pathways, and inhibiting tumor cell proliferation." (PMID 41472727, 2025). "These co-occurring tumor genomic alterations are not necessarily mutually exclusive, and evidence suggests that multiple clonal and sub-clonal cancer cell populations can co-exist and contribute to EGFR TKI resistance." (PMID 39852181, 2025). "However, these methods have inherent limitations: biopsies are invasive and unsuitable for repeated monitoring, tumor heterogeneity can lead to inaccurate results, and neither biopsy nor IHC provides real-time, whole-body EGFR expression data." (PMID 40906195, 2025).
tumor (continued). "TAVO412 had stronger tumor growth inhibition than amivantamab and cetuximab, since the design had more engineered MOA that included: angiogenesis control by the anti-VEGF arm; enhanced ADCC, ADCP, and CDC mediated by the unique dual-epitope EGFR and cMET binding epitopes." (PMID 40452841, 2025). "Conversely, concerns have been raised about PRP promoting tumor growth due to growth factors such as platelet-derived growth factor (PDGF), vascular endothelial growth factor (VEGF), epidermal growth factor receptor (EGFR or HER), and transforming growth factor-beta (TGF-β)." (PMID 40399731, 2025). "Moreover, the combination of anlotinib with benmelstobart produced encouraging tumor responses in advanced NSCLC lacking EGFR or ALK alterations, with generally manageable toxicities." (PMID 40908570, 2025). "For instance, dual blockade of EGFR and MET may overcome MET-amplified or MET-driven resistance, whereas combining EGFR-TKIs with PD-1/PD-L1 inhibitors can potentially counteract TKI-induced upregulation of PD-L1 and the induction of an immunosuppressive tumor microenvironment (TME)." (PMID 41472727, 2025). "Notably, while OS resistance to chemotherapy remains an active area of research, the role of EGFR signaling and functional contributions, such as hyperactivation, to tumor biology and chemoresistance in OS are still not fully understood." (PMID 39796763, 2025). "In addition to a number of reported mRNA transcripts, such as ILEI, EGFR, MOESIN, FAM3C, JAK2 and EIF5A2, we identified ZEB2, an EMT‐related transcription factor that is vital for tumor metastasis, as a potential transcript regulated by PCBP1 at the translational level." (PMID 41117067, 2025). "In terms of spatial localization, we also found that the neural-signal-related ligand CDH1 interacts with EGFR mainly in the tumor surrounding area, which may promote tumor invasion into normal tissues." (PMID 41147013, 2025). "Signaling pathway activation and tumor cell survival: hepatocyte growth factor (HGF) secreted by CAFs activates the c-Met receptor and restores PI3K/Akt and MAPK/ERK signaling, leading to epidermal growth factor (EGFR)-tyrosine kinase inhibitor (TKI) resistance." (PMID 41346633, 2025). "Additionally, the anti-tumor activity of ATR-I was diminished after KIF15 overexpression in AR+ and AR− CRPC cells, indicating that KIF15 expedited CRPC progression in both an AR-dependent- and independent manners, such as the EGFR signaling pathway." (PMID 40087774, 2025). "In a study using paired tumor samples, the density of Tregs shifted from negative or low at baseline to high after the development of EGFR-TKI resistance in programmed death-ligand 1 (PD-L1)-negative or -positive tumors, indicating an immunosuppressive role of Tregs in oncogene-driven tumors." (PMID 40002883, 2025). "Drugs against defined drivers (e.g., EGFR) offer new options for patients with advanced or recurrent OSCC, while immune checkpoint inhibitors (ICIs), such as PD-1/PD-L1 inhibitors, have shown encouraging clinical activity by reinvigorating anti-tumor immune responses." (PMID 41374963, 2025). "Although no significant statistical difference was found due to small samples, the lower EGFR mutation rate of IPF patients was also observed in non-smokers, suggesting that the presence of IPF itself was negatively correlated with tumor EGFR mutation, which was similar to previous reports." (PMID 40507634, 2025). "Based on these data, it seemed unclear whether Ras-driven cell extrusion would require EGFR activity or not, even though the necessity for EGFR signaling in K-Ras tumor models is incontestable." (PMID 41132131, 2025).
tumor (continued). "However, VEGF blockade does not directly interfere with tumor-intrinsic signaling pathways, whereas EGFR inhibition does." (PMID 40076838, 2025). "Similarly, mutations in KRAS, particularly G12C, could alter the tumor’s response to targeted therapies like EGFR-TKIs and MEK inhibitors by activating downstream MAPK and PI3K/AKT/mTOR pathways that promote tumor survival and drug resistance." (PMID 41560751, 2025). "Interestingly, the antitumor efficacy of rLZ-8 on five patient-derived tumor xenograft (PDX) models of HCC (LI6280, LI1097, LI0050, LI0334, LI6611) was directly correlated with tumoral EGFR expression levels, suggesting the mechanistic involvement of EGFR." (PMID 40733125, 2025). "Furthermore, EGFR T790M/L858R-mutant non-SCLC cells produce EVs that accelerate the tumor growth by enhancing invasion, migration, and proliferation." (PMID 40530018, 2025). "However, fetal tumor and embryonal tumor organoids exhibited differential sensitivity to receptor tyrosine kinase inhibitors: embryonal organoids were sensitive to FGFR inhibitors, but fetal organoids responded to EGFR inhibitors." (PMID 40684183, 2025). "The immunological characteristics of EGFR could justify its integration into immunoPET strategies, not only as a tumor biomarker but also as an immunologic imaging target." (PMID 41211421, 2025). "Consequently, M2 macrophages are regarded as potential biomarkers of tumor aggressiveness and therapeutic targets, particularly in combination with HIF inhibitors, metabolic agents, or immunotherapeutic strategies targeting the EGFR/VEGFR signaling pathways." (PMID 40843751, 2025). "Thus, our discovery of the unannotated HELDR that coamplifies with EGFR in GBM ecDNAs and is transcribed in the antisense strand of the ELDR locus suggests that additional lncRNAs could be found in tumor ecDNAs and in the antisense strand of known gene loci." (PMID 40678238, 2025). "This synergy may stem from chemotherapy’s nontargeted mechanisms counteracting tumor heterogeneity to delay EGFR-TKI resistance." (PMID 40871064, 2025). "Furthermore, our findings indicated that MIG-6 may regulate the EGFR/AKT pathway and promote tumor growth and metastasis." (PMID 40535815, 2025). "Another study showed that the mean tumor-to-background ratio (TBR) increased with dose (3.6 at 50 mg versus 4.3 at 100 mg) and was significantly higher in contrast-enhancing tumors than in nonenhancing ones (4.0±0.5 versus 1.2±0.3; p=0.02), confirming the feasibility of EGFR-targeted imaging." (PMID 41346398, 2025). "However, given the expected phenotypic differences that a non-tumor cell type implies, the validity of CHO-K1 cells as an EGFR− reference model could be arguable." (PMID 40006027, 2025). "Each cell line overexpresses αvβ6, required for Ad5NULL-A20 transduction, and EGFR and MICA (including other NKG2D ligands) required for BICA activation, therefore possess the required characteristics to demonstrate T cell activation and tumor cell lysis by CD3-BICA." (PMID 40741595, 2025). "Overall, alterations in EGFR and ALK genes are relatively rare in primary PLEC However, there may still be some special cases with EGFR or ALK gene alterations that interact with other factors or are related to individual differences of patients, tumor heterogeneity, or detective methods." (PMID 40881855, 2025). "Moreover, PRDX1 may play an important role in modulating EGFR-TKI therapeutic sensitivity and tumor immunity, highlighting its promise as a therapeutic target to improve clinical outcomes in LUAD." (PMID 40303499, 2025). "Cetuximab is a monoclonal antibody targeting the epidermal growth factor receptor (EGFR), which is a member of the human epidermal growth factor (HER)/ErbB family of receptor tyrosine kinases, wherein activation is known to induce survival and tumor growth of cancer cells." (PMID 40076457, 2025).